DDB2 (damage specific DNA binding protein 2)
Diseases named in the same sentence as DDB2 in open-access papers (continued):
Sharing a sentence is not in itself a finding about the gene and the disease.
cancer (continued). "In contrast, we observed significantly higher expression of DDB2 in both normal tongue tissues and cancer adjacent normal tissues (NAT)." (PMID 30410671, 2018). "Another study revealed that DDB2 over-expression within a cancer cell line led to higher cisplatin sensitivity through an increase in apoptosis." (PMID 26263968, 2015). "In young individuals increased DDB2 expression is beneficial to prevent cancer by induction of senescence and apoptosis." (PMID 23109835, 2012). "In conclusion, the discoveries on DDB2’s transcriptional function have revealed several interesting possibilities that can be explored in designing novel therapeutics for the treatment of cancer and aging." (PMID 23109835, 2012). "In support of that notion, a recent reported that expression of DDB2 sensitizes cancer cells to therapy." (PMID 20205757, 2010). "Consistent with that, a search of the Oncomine database revealed that DDB2 is one of the top 10% under-expressed genes in a variety of cancers." (PMID 20205757, 2010). "A corollary to these observations is that reduced expression of DDB2 would lead to drug resistance of cancer cells." (PMID 20205757, 2010). "This suggests a role of DDB2 as a tumor suppressor in normal cells, through protecting against cancer by regulating the cell cycle and by increasing apoptosis rather than by direct participation in the repair of DNA damage." (PMID 18431487, 2008). "The functional role of DDB2 in cancer is complex and context-dependent." (PMID 41208896, 2025). "Targeting DDB2 with lapatinib represents a promising therapeutic strategy to overcome chemoresistance and improve the efficacy of DNA-damaging chemotherapies across multiple cancer types." (PMID 41208896, 2025). "However, DDB2 also has other functions, such as regulation of cell-cycle and transcription, and it appears to have a dual role in cancer." (PMID 39335143, 2024). "Moreover, introduction of the DDB2 gene into triple-negative MDA-MB231 cells stimulated growth and colony formation, while DDB2 knockdown in MCF-7 BC cells caused a decrease in cancer cell growth and colony formation." (PMID 39335143, 2024). "However, increasing evidence suggests that DDB2 exhibits dual functions in cancer cell proliferation." (PMID 35288483, 2022). "However, DDB2 is reported to have dual functions in cancer, sometimes with tumor suppressive properties and sometimes functioning as an oncogene." (PMID 36033456, 2022). "Moreover, we found that the genes encoding for the NER-related molecular components of the heterodimer DDB complex (DDB1 and DDB2) were upregulated in cancer patients." (PMID 35740268, 2022). "DDB2 levels may also affect the effectiveness of anticancer drugs in cancer treatment and be used as a prognostic factor for the sensitivity of patients with cancer to chemoradiotherapy." (PMID 36190612, 2022). "This article explored the roles of DDB2 in biological processes that may affect cancer, including NER, apoptosis, and premature senescence." (PMID 36190612, 2022). "In cancer cells, DDB2 may also promote the repair of cancer DNA lesions induced by radiation or chemotherapy leading to chemo/radioresistance." (PMID 36033456, 2022). "DDB2 was a component of the damage-specific DNA-binding heterodimeric complex, which is involved in the occurrence and development of premature ageing and cancer by affecting nucleotide excision repair (NER) and cell apoptosis." (PMID 36672781, 2022). "DDB2 also affects the sensitivity of cancer cells to radiotherapy and chemotherapy." (PMID 36190612, 2022). "However, DDB2 plays a dual role in carcinogenesis by regulating the growth and apoptosis of cancer cells." (PMID 36190612, 2022). "Our results broaden the horizon for understanding the opposite function of CDT2 and DDB2 in tumorigenesis, and may provide clues for drug discovery in cancer therapy." (PMID 33557942, 2021). "DDB2 has been reported to be abnormal expressed in several cancers." (PMID 32090112, 2020).
cancer (continued). "Because DNA repair serves as an anti-cancer barrier in early human tumorigenesis, arecoline-induced DDB2 downregulation and impaired NER activity may contribute to cancer development and, as a result, may lead to a high incidence of HNC among BQ chewers." (PMID 32722430, 2020). "As an important DNA damage-binding protein in the NER pathway, the alternation expression of DDB2 might affect the DNA repair capacity and thus contribute to cancer development, including HCC." (PMID 32090112, 2020). "We also provide insights into the clinical consequences of DDB2 activity in cancers." (PMID 31635251, 2019). "Thus, the favorable prognosis of cancer patients with high DDB2 expression can be attributed to DDB2-promoted reduction of the CSC pool." (PMID 29752431, 2018). "Metastatic progression of cancer often coincides with reduced expression of DDB2." (PMID 30410671, 2018). "Thus, DDB2 functions converge on inhibiting cancer promoting events and DDB2 itself is found to be directly involved in lesion-independent binding to DNA and suppressing the transcription of genes directly involved in tumor progression." (PMID 30410671, 2018). "Overexpression of DDB2 could sensitize the cancer cells to cisplatin treatment which indicated that DDB2 may play important role in platinum-based chemotherapy." (PMID 28924235, 2017). "Further, DDB2 expression is attenuated in a wide variety of cancers at the RNA level." (PMID 23109835, 2012). "Elevated levels of DDB2, through its ability to activate cancer cell growth, may influence the effectiveness of anticancer drugs." (PMID 18431487, 2008). "However, the function of DDB2 appears to be context-dependent across different cancers." (PMID 41208896, 2025). "The new evidence that DDB2 interacts with NF-kB remarkably supports the hypothesis that DDB2 may be involved in early transcriptional events occurring before metastases formation thus inhibiting cancer progression." (PMID 38773406, 2024). "DDB2 may also target other proteins for degradation during tumor progression and affect several stages of carcinogenesis, such as cancer cell proliferation, survival, epithelial-to-mesenchymal transition, migration and invasion, angiogenesis, and cancer stem cell formation." (PMID 36190612, 2022). "Additionally, our study revealed that NTMT1, which methylates the α-N-terminal amines of proteins [e.g., RCC1 (regulator of chromosome condensation 1), CENPA (centromere protein A), and DDB2 (damage specific DNA binding protein 2)], likely possesses cancer-promoting roles." (PMID 34285249, 2021). "Given that DDB2 silencing promotes the cancer cell dedifferentiation, and ALDH1A1 plays a critical role in DDB2 silencing-induced expansion of the CSC subpopulation, we sought to determine whether ALDH1A1 is essential for DDB2 silencing-augmented non-CSC-to-CSC conversions." (PMID 29752431, 2018). "In addition, DDB2 reportedly acts as a tumor suppressor in a wide range of cancers." (PMID 28212551, 2017). "However, this phenomenon may be explained by the fact that DDB2, in addition to its role as a tumor suppressor in many cancers DDB2 also acts as damaged DNA binding protein to detect cancer chromosome instability." (PMID 28212551, 2017). "Interestingly, the DDB2−/− mice also develop spontaneous malignant tumor at a very high frequency." (PMID 23109835, 2012). "Hence, it is important to recognize how DDB2 expression is lost during carcinoma progression and will be important to determine whether restoration of DDB2 expression helps to prevent tumor development." (PMID 23109835, 2012). "However, strong evidence for the functional interaction between DDB2 and E2F1, a proliferative marker in many cancers led us to speculate that DDB2 could be involved also in cancer cell growth." (PMID 18431487, 2008).
cancer (continued). "In addition, DDB2-deficient mice not only were hypersensitive to UV-induced skin carcinogenesis but also developed a high rate of broad spectrum spontaneous malignant tumors in internal organs, in the absence of UV irradiation or added carcinogen." (PMID 18431487, 2008). "DDB2 expression was positively correlated with the half-maximal inhibitory concentration (IC50) values for doxorubicin, cisplatin, and 5-FU across pan-cancer cell lines, indicating that higher DDB2 levels are associated with reduced drug sensitivity." (PMID 41208896, 2025). "For instance, GSTO2 and PGF were down-regulated while CSF1R, DDB2, HMOX1 and PGFB were up-regulated in both cancers." (PMID 38790250, 2024). "Survival of the cancer cells is optimized through the up-regulation of several key genes, ensuring evading apoptosis such are BIRC5 (x(T) = 6.04) and DDB2 (x(T) = 2.37)." (PMID 38790250, 2024). "DDB2, a multifunctional WD40 repeat protein, can modulate DNA repair and cancer development through numerous mechanisms." (PMID 35813480, 2022). "Damage specific DNA binding protein 2 (DDB2) is an UV-indiced DNA damage recognition factor and regulator of cancer development and progression." (PMID 36568213, 2022). "It will be of interest to determine the functional link between DDB2 and LRH-1 in cancer progression and pathogenesis." (PMID 30923324, 2019). "Moreover, Damage Specific DNA Binding Protein 2 (DDB2) is involved in DNA repair machinery, cancer development, and the cancer response to chemotherapy." (PMID 40426689, 2025). "The UV‐DDB complex, including DDB1 (LoH: 10.4%) and DDB2 (LoH: 8.0%), facilitates binding of XPC to UVR‐induced lesions, and experimental evidence suggests its knockdown increases tumorigenic potential and reduces overall survival in various cancers." (PMID 35229492, 2022). "This lack of correlation between basal DDB2 expression level and cell origin was also found in several cell lines from other cancer sites." (PMID 36568213, 2022). "Several studies highlighted an altered DDB2 expression, compared to non-malignant tissues, in many types of cancers, including prostate, colorectal, skin, head and neck, and ovarian cancers." (PMID 31635251, 2019). "In the same way, DDB2 restricts the transcription of the pro-angiogenic growth factor VEGF (vascular endothelial growth factor) and thus contributes to the inhibition of cancer cell invasion and metastasis formation." (PMID 31635251, 2019). "Here, we demonstrated that the ovarian CSC subpopulation can be maintained via cancer cell dedifferentiation, and DDB2 is able to suppress this non-CSC-to-CSC conversion by repression of ALDH1A1 transcription." (PMID 29752431, 2018). "It is not excluded that the decrease in DDB2 expression is associated with a decrease in the NER system and an accumulation of unrepaired DNA damage, leading to an invasive cancer phenotype." (PMID 18431487, 2008). "No study has yet investigated TBCB or DDB2 isoforms in connection with cancer." (PMID 39335143, 2024). "Next, we checked the Cancer Cell Line Encyclopedia (CCLE), an open resource of large-scale genetic and chemical characterizations of cancer cell lines, in a search for an EC cell line to validate the correlation of the expressions between PTEN and DDB2 observed in TCGA." (PMID 37142958, 2023). "The role of DDB2 downregulation in patients’ worse outcomes may be due to its role in suppressing epithelial-to-mesenchymal transition (EMT), which is a process involved in metastasis and chemoresistance of cancer cells." (PMID 32722430, 2020). "It reveals that DDB2 promotes the ubiquitination and degradation of a newly identified tumor suppressor PAQR3 (progestin and adipoQ receptor family member III) that limits cancer development and progression, notably inhibiting cancer cell migration, invasion, and angiogenesis." (PMID 31635251, 2019).
cancer (continued). "The expression of breast cancer 1, early onset (BRCA1), RAD51, bloom syndrome, RecQ helicase-like (BLM), flap-endonuclease 1 (FEN1), uracil-DNA glycosylase (UNG), damage-specific DNA binding protein 2 (DDB2) and exonuclease 1 (EXO1) were significantly suppressed after 24 h ZEA treatment." (PMID 24788721, 2014).
tumor (50 papers, 2008 to 2026). "It has been reported that tumours with DDB2 deficiency should be more sensitive to DNA-damaging treatments, such as platinum products." (PMID 38773406, 2024). "In fact, a number of these cullins-associated E3 ligases, such as Fbxo31, Keap1, DDB2, and the cullins, have been demonstrated to function as tumor suppressors or components of tumor suppressor complexes." (PMID 37943017, 2023). "Mechanistically, MBD2 selectively binds to the methylated CpG DNA within the DDB2 promoter, by which it represses DDB2 expression predisposing to tumor metastasis." (PMID 37142578, 2023). "DDB2 has been characterized as a tumor suppressor gene as its mutation results in NER defects and consequential genetic instability." (PMID 35428778, 2022). "Loss of DDB2 function in normal cells is related to tumor development susceptibility." (PMID 18431487, 2008). "Loss of DDB2 function may be related to tumor susceptibility." (PMID 18431487, 2008). "DDB2 has been implicated in the regulation of DNA damage repair and protein degradation, and our results indicate that DDB2-mediated ubiquitination of POLR2A/B/E is a key driver of PF-3758309’s anti-tumor effects." (PMID 40854914, 2025). "In ovarian cancer, DDB2 acts as a tumour suppressor by reducing the self-renewal capacity of OvCa stem cells." (PMID 41008855, 2025). "To assess the oncogenic relevance of DDB2, we analyzed its basal expression across normal and tumor tissues." (PMID 41208896, 2025). "Although the role of DDB2 in tumor progression is context-dependent, its upregulation has been associated with poor prognosis in various malignancies." (PMID 41208896, 2025). "DDB2's dual function, as a DNA repair protein and transcriptional regulator 48, likely contributes to its ability to act either as a tumor suppressor or promoter, depending on the cellular context." (PMID 41208896, 2025). "In OvCa cells, DDB2 is targeted and downregulated by miR-328-3p, which impairs its tumour-suppressive activity." (PMID 41008855, 2025). "In conclusion, our study reveals a novel anti-tumor mechanism of PF-3758309, which involves the DDB2-mediated degradation of POLR2A/B/E through the ubiquitin-proteasome system." (PMID 40854914, 2025). "Collectively, our data support that MBD2 promotes tumor metastasis by enhancing EMT via attenuating DDB2 expression." (PMID 37142578, 2023). "As the expression level of DDB2 in PC tissues is lower than in non-tumor tissues, the balance between NRIP and DDB2 is disrupted." (PMID 36190612, 2022). "DDB2 was originally identified as a novel tumor suppressor via nucleotide excision repair, and it is abnormally expressed in several tumor tissues." (PMID 35288483, 2022). "A recent study found higher expression levels of nuclear receptor-interacting protein (NRIP) and androgen receptor (AR) and lower DDB2 expression in PC tissues than in non-tumor tissues." (PMID 36190612, 2022). "DDB2 (DNA damage binding protein 2) is one of the key DNA repair proteins which is assumed to have tumor‐suppressing features and contribute to better treatment responses in tumors." (PMID 34923780, 2022). "Tumor staining in DDB2-knockout mice showed that the expression of the Wnt signaling inhibitor RNF43 (ring finger protein 43) decreased and the mRNA expression of the Wnt target gene Cdx1 increased." (PMID 36190612, 2022). "The results revealed that tumor tissues had significantly higher expression of DDB2, MSI2, and RBM15 than the normal tissues." (PMID 35288483, 2022). "DDB2 participates in many biological processes including gene transcription and cell cycle regulation and is identified as a critical factor in tumor development." (PMID 34869021, 2021). "Next, the expression of DDB2 mRNA in 92 HNC specimens was compared with that in adjacent non-tumor tissues by using RT-qPCR." (PMID 32722430, 2020).